USP39 (ubiquitin specific peptidase 39)
Diseases named in the same sentence as USP39 in open-access papers (continued):
Sharing a sentence is not in itself a finding about the gene and the disease.
cancer (continued). "With elevated expression in these cancers, USP39 promotes tumor cell growth, proliferation, invasion, migration and other malignant behaviors." (PMID 40672756, 2025). "In summary, USP39 plays a critical regulatory role in malignant tumors as well as in various physiological and pathological processes, underscoring its significance as an essential regulatory molecule in the human body." (PMID 40672756, 2025). "This work introduces a novel approach to designing inhibitors by leveraging USP39’s functional and structural characteristics, paving the way for new therapeutic avenues in cancer research." (PMID 40672756, 2025). "Collectively, this work identifies the first DUB for RBM39 and elucidates the regulatory functions and the underlying mechanism, providing a possible alternative approach to suppressing RBM39 by inhibiting USP39 in cancer therapy." (PMID 39260689, 2024). "It has also been revealed that USP39 regulates cell proliferation, migration, invasion, and apoptosis of several cancers, including colon cancer, glioma, and hepatocellular carcinoma." (PMID 39260689, 2024). "Previous studies have shown that USP39 is significantly involved in the occurrence and development of cancer." (PMID 38459014, 2024). "The DUB USP39 is known for its role in regulating alternative splicing and has been reported to promote carcinogenesis and cancer progression through deubiquitination." (PMID 39695108, 2024). "Both as an alternative splicing regulator and as a DUB, USP39 has been shown to promote cancer progression." (PMID 39695108, 2024). "Overexpression of USP39 facilitates constitutive splicing of individual pre-mRNAs in different cancers." (PMID 37821439, 2023). "Previous studies have reported that USP39 contributes to cancer progression in various human tumor types and acts as a splicing factor." (PMID 35627203, 2022). "For example, USP39 can promote the proliferation and growth of cancer cells in colon cancer cells, pancreatic cancer cells, and gastric cancer cells." (PMID 36046375, 2022). "In functional experiments, we demonstrated that USP39 not only promotes the proliferation of cancer cells but also influences cell migration, invasion, and chemoresistance in ESCC." (PMID 35627203, 2022). "Many studies have shown that USP39 is overexpressed in a variety of cancer cells and acts as a carcinogenic factor." (PMID 36046375, 2022). "Several studies have demonstrated that ubiquitin‐specific protease 39 (USP39) plays an oncogenic role in various cancer types." (PMID 33811456, 2022). "In conclusion, overexpression of miR-381 can regulate the expression of USP39, inhibit the proliferation and invasion of cancer cells, and induce apoptosis of cancer cells." (PMID 36046375, 2022). "Emerging evidence revealed that the aberrant expression of USP39 plays vital roles in tumorigenesis and tumor progression in various cancer types." (PMID 35627203, 2022). "Previous studies have reported that USP39 acts in an oncogenic manner where it contributes to cancer progression and predicts poor prognosis in various human tumor types." (PMID 34123832, 2021). "Ubiquitin-specific peptidase 39 (USP39) serves as the pro-tumor factor in several previous studies of other malignant tumors." (PMID 34544400, 2021). "According to the pan-cancers analysis in TIMER dataset, the most significant difference of USP39 between pan-cancers and normal tissues was observed in HCC." (PMID 33718205, 2021). "Inhibition of SUMOylation of USP39 enhanced the proliferation of cancer cells as it affected the recruitment of tri-snRNP, suggesting that SUMOylation of USP39 plays an essential role in cancer therapy." (PMID 34177595, 2021). "Overexpression of USP39 was observed in approximately half of the pan-cancers in TCGA dataset, of which HCC displayed the most differences between normal and tumor tissues." (PMID 33718205, 2021).
cancer (continued). "Previous studies have shown that USP39 is commonly upregulated in various human cancers including ovarian cancer." (PMID 33731694, 2021). "We found the USP39 upregulation was maintained in ESCC cell lines where it functioned to promote cancer cell growth in vitro and in xenografts." (PMID 34123832, 2021). "Previous studies have reported that USP39 contributes to cancer progression and predicts poor prognosis in various human tumor types." (PMID 34123832, 2021). "Analyses of public datasets together with our cohort of tissues now add ESCC to the list of cancers where USP39 likely contributes to disease progression." (PMID 34123832, 2021). "Previous studies have reported that USP39 contributes to cancer progression and predicts poor prognosis in various tumors." (PMID 31332287, 2019). "Knockdown of USP39 in PCa cells inhibited cancer colony formation and tumor cell growth, and induced G2/M arrest and cell apoptosis." (PMID 26959883, 2016). "Notably, among the many research articles on USP39, the role of USP39 in the development of cancer is particularly notable." (PMID 40990019, 2025). "As a key regulator of malignant progression of malignant tumors, USP39 is abnormally overexpressed in the tissues and cells of malignant tumors, and plays a role in modulating diverse biological processes, including tumor cell growth, proliferation, invasion, cell cycle progression, and apoptosis." (PMID 40672756, 2025). "Moreover, we particularly focus on the aberrant expression of USP39 in various cancers and its effect on cancer markers, as well as on the regulatory role of USP39 in tumor progression." (PMID 40990019, 2025). "USP39 regulates p21 stability to modulate cancer progression." (PMID 40990019, 2025). "Additionally, this review will examine the pathological significance of USP39 in the progression of various cancers and other diseases, with a particular focus on its emerging role in mediating immune evasion and immunotherapy resistance." (PMID 40990019, 2025). "Furthermore, USP39 can cooperate with multiple oncogenic factors to promote tumorigenesis in malignant tumors." (PMID 40672756, 2025). "Furthermore, the study examines USP39’s contribution to resistance against antitumor therapies, highlighting its clinical relevance in advancing cancer treatment strategies." (PMID 40672756, 2025). "Effects of USP39 on growth and metastasis of cancer xenografts." (PMID 40672756, 2025). "As the PI3K/AKT pathway is common in various cancers, we verified whether USP39 could stimulate PI3K/AKT/HIF-1α signaling to accelerate glycolysis." (PMID 38459014, 2024). "Overall, our findings underscore the significant role of USP39 in MM cancer progression." (PMID 39736693, 2024). "USP39 is overexpressed in various cancers, promoting cancer progression." (PMID 39062505, 2024). "While the oncogenic function of USP39 has been investigated in various cancer types, its roles in non-small cell lung cancer (NSCLC) remain largely unknown." (PMID 39695108, 2024). "USP39 and possibly other mid/late-acting spliceosome proteins may represent potential prognostic biomarkers and targets for cancer therapy." (PMID 37821439, 2023). "In addition, numerous studies showed that USP39 was involved in cancer progression in various human tumor types and functions as a splicing factor." (PMID 36707504, 2023). "Here, we found that USP39 promotes cancer cell growth and chemoresistance in ESCC." (PMID 35627203, 2022). "Moreover, an oncogenic function of USP39 has been identified in a variety of cancer types, including lung and colon carcinomas, human renal cell carcinoma, breast cancer as well as other cancers." (PMID 33811456, 2022). "Exploration of the level of USP39 in various human cancers was carried out in TIMER and Oncomine." (PMID 34987596, 2021). "Furthermore, our study adds ESCC to the list of cancers where USP39 contributes to tumorigenesis and progression." (PMID 34123832, 2021).
cancer (continued). "Moreover, other studies have suggested that USP39 functions as an oncogenic factor in numerous cancers including breast, liver, medullary thyroid, lung, prostate, oral squamous cell and renal cell carcinomas." (PMID 34123832, 2021). "ZEB1 is a crucial inducer of EMT to promote the metastasis of cancer cells, but whether its stability is regulated by USP39 or TRIM26 in HCC remains enigmatic." (PMID 33649471, 2021). "Recently, several studies have reported that USP39 is abnormally expressed in various different malignant tumors and may function as a tumor promotor." (PMID 33255748, 2020). "Moreover, recent studies indicated that knocking down USP39 promoted cell proliferation in different types of cancers." (PMID 33255748, 2020). "Previous studies determined that USP39 functions as an oncogenic factor in various types of cancer." (PMID 33255748, 2020). "For example, USP39 has been shown to be essential for KRAS-driven cancer." (PMID 31332287, 2019). "We first analyzed USP39 expression in human cancer in the publicly available database Oncomine." (PMID 31332287, 2019). "The roles of USP39 in human cancer have been widely investigated." (PMID 30898977, 2019). "Previous reports demonstrated that USP39 was significantly involved in diverse types of cancer." (PMID 30898977, 2019). "Recently, some studies have reported the role of USP39 in cancer cell growth." (PMID 26303214, 2015). "Although lentivirus could efficiently deliver shRNA into mammalian cells and silencing USP39 in carcinoma cells, targeted gene delivery methods are need to be developed to specifically knockdown USP39 expression in tumor cells." (PMID 25889525, 2015). "It is important to highlight that USP39 serves as a tumor-promoting factor in the majority of malignant cancers, and the combination of cisplatin and USP39 inhibitors may effectively improve the sensitivity of patients to the drug and enhance the therapeutic effect." (PMID 40672756, 2025). "Notably, while the majority of USP family members regulate malignant tumors at the protein modification level, emerging evidence indicates that USP39 contributes to tumor progression by modulating the splicing of pre-mRNA associated with tumors during post-transcriptional modification." (PMID 40672756, 2025). "Importantly, targeting USP39 may overcome resistance to checkpoint inhibitors, offering a promising approach to enhance cancer immunotherapy efficacy." (PMID 40990019, 2025). "Therefore, USP39 is a strong regulator for cell cycle and apoptosis in diverse types of cancer." (PMID 30898977, 2019). "The ubiquitin-specific protease 39 (USP39) has been widely investigated and shown to be critical for multiple cancer-promoting processes including alternative splicing, regulation of the cell cycle, and DNA damage repair." (PMID 39695108, 2024). "Taken together, our study demonstrates that USP39 serves as an oncogenic factor in ESCC through promoting tumor proliferation in vivo and in vitro, improving invasion and migration of cancer cells and inhibiting the cell apoptosis with the treatment of DDP." (PMID 35627203, 2022). "A major part of cancer promoting genes were embryonic neural specific, including genes for deubiquitases USP7 and USP39." (PMID 31130994, 2019). "Ubiquitin specific peptidase 39 (USP39), an essential factor in the assembly of the mature spliceosome complex, has an aberrant expression in several cancer." (PMID 28403900, 2017). "Interestingly, miR-381 was able to bind to a site on the USP39 3′UTR sequence in NSCLC and was equally effective in inhibiting cancer cell development by suppressing USP39 expression." (PMID 40672756, 2025). "USP39 is frequently overexpressed in various cancer tissues compared to the corresponding non-neoplastic tissues." (PMID 39695108, 2024).
cancer (continued). "Understanding the interplay between USP39 and ETS2 may have implications for therapeutic interventions targeting ETS2-related diseases, including cancer, where the dysregulation of ETS2 is frequently observed." (PMID 37892157, 2023). "No denying many studies have proved that USP39 plays a cancer-promoting role in HCC, however, the regulation of splicing and deubiquitination that USP39 played in the development of HCC remains to be further studied." (PMID 36707504, 2023). "However, until now, no metabolic enzyme as a direct target of USP39-mediated deubiquitination has been identified that changes cancer metabolism." (PMID 39695108, 2024). "Two genes PLK3 and USP39 were not covered by any representative term and none of them is an NCG cancer gene." (PMID 34504716, 2021).
tumor (41 papers, 2015 to 2025). "Studies have shown that USP39 is abnormally expressed in various types of malignancies and is strongly associated with tumor stage and patient prognosis." (PMID 40990019, 2025). "Conversely, deletion of USP39 in Tregs induces a strong anti-tumor immune response by blocking tumor-associated Tregs activity." (PMID 40990019, 2025). "The upregulation of USP39 in ESCC was found to be associated with tumor differentiation, invasion, lymph node metastasis and TNM stage." (PMID 34123832, 2021). "Univariate Cox regression analysis showed that high expression of USP39 was significantly associated with advanced T stage, pathological stage, and tumor status." (PMID 34987596, 2021). "Clinicopathologic analysis revealed that USP39 overexpression was associated with advanced tumor stage and platinum resistance." (PMID 33731694, 2021). "Logistic analysis demonstrated that high expression of USP39 was significantly associated with older age, tumor status, advanced pathologic stage, T stage, and higher histologic grade." (PMID 34987596, 2021). "Results showed that high expression of USP39 was associated with T stage, pathologic stage, tumor status, age, and histologic grade." (PMID 34987596, 2021). "In the present study, logistic analysis demonstrated that high expression of USP39 was significantly associated with tumor status, advanced pathologic stage, T stage, and high histologic grade, which was basically consistent with those of the previous studies." (PMID 34987596, 2021). "In addition, overexpression of USP39 accelerated the tumor growth and reversed the 2-DG-caused tumor inhibition." (PMID 38459014, 2024). "Loss of USP39 in U251 cells significantly prolonged survival of the tumor‐bearing mice (P < 0.001)." (PMID 33811456, 2022). "USP39 regulates the cell cycle and tumor growth of HCC cells by facilitating the deubiquitylation pathway of the SP1 protein, stabilizing its protein level, and prolonging its half-life." (PMID 40990019, 2025). "miR-381 controls tumor proliferation and invasion by negatively regulating USP39 expression, providing a new idea for targeted therapy of NSCLC." (PMID 40990019, 2025). "Lactate enhances CTLA-4 expression in tumor-infiltrating Treg cells by promoting USP39-mediated RNA splicing in a Foxp3-dependent manner, thereby sustaining Treg function in the tumor microenvironment." (PMID 40535811, 2025). "In vivo and in vitro assays have demonstrated that USP39 knockdown suppresses tumor growth, inhibits cell proliferation, and blocks the G2-to-M phase transition of the cell cycle." (PMID 40672756, 2025). "In vitro experiments have shown that USP39 positively regulates several biological functions of tumor cells." (PMID 40672756, 2025). "First, USP39 can influence malignant tumor progression through multiple regulatory mechanisms simultaneously." (PMID 40672756, 2025). "In human HCC cells, USP39 has been shown to facilitate tumor proliferation in a spliceosome-dependent manner, which is partly mediated by the oncogenic splice switch in the focal adhesion protein gene KANK2." (PMID 40990019, 2025). "On this basis, the combined use of drugs that inhibit both USP39’s binding functions and splicing regulatory functions can exert multifaceted inhibitory effects, effectively suppress tumor progression and enhance therapeutic efficacy." (PMID 40672756, 2025). "Functional approaches have demonstrated that USP39 plays a key role in supporting tumor cell proliferation and survival as demonstrated by short-hairpin mediated down regulation and over-expression using cell growth and colony forming assays." (PMID 39430244, 2024). "Taken together, our data show that USP39 regulated pyruvate handling and is crucial for cell proliferation in vitro and tumor growth in vivo." (PMID 39695108, 2024). "CCK-8 and colony formation assays suggested that the downregulation of USP39 inhibited the proliferation of tumor cells." (PMID 38459014, 2024).